MIF (macrophage migration inhibitory factor)
Diseases named in the same sentence as MIF in open-access papers (continued):
Sharing a sentence is not in itself a finding about the gene and the disease.
osteosarcoma (22 papers, 2008 to 2025). A usually aggressive malignant bone-forming mesenchymal neoplasm, predominantly affecting adolescents and young adults. "MIF was significantly increased in tissue and serum samples from osteosarcoma patients (OS) and was associated with their tumor size, lung metastasis, and survival." (PMID 36613737, 2022). "Additionally, genes like COL6A1, COL6A3, and MIF were associated with lung metastasis, indicating that a highly invasive subcluster in osteosarcoma correlated with a poor prognosis." (PMID 39324133, 2024). "Mechanistic studies have further shown that MIF facilitates osteosarcoma cell proliferation and metastasis by activating the RAS/MAPK signaling axis, with the degree of pathway activation closely tied to tumor burden and patient prognosis." (PMID 41127012, 2025). "Collectively, these data suggest that MIF is expressed by osteosarcoma cells and that CXCL12 is expressed by peritumoral stromal and/or immune cells." (PMID 39896512, 2025). "The osteosarcoma microenvironment exhibited marked immune remodeling with T/NK infiltration, enrichment of Tregs and M2 macrophages, and enhanced MIF-mediated crosstalk driving immune evasion." (PMID 41346635, 2025). "Complementing this, cell-cell communication analysis demonstrated enhanced signaling through the MIF pathway between Mal_Ost/Cho and T/NK cells, validating the MIF-mediated intercellular communication axis enables immune evasion in osteosarcoma." (PMID 41346635, 2025). "Since U2OS cells were isolated from an osteosarcoma, they express MIF at a higher level than normal osteoblast cells." (PMID 38799575, 2024). "As an inflammatory factor and oncogenic driver protein, the pleiotropic cytokine macrophage migration inhibitory factor (MIF) plays a crucial role in the osteosarcoma microenvironment." (PMID 35060345, 2022). "In terms of the MIF content, multiple osteosarcoma cell lines (MG63, HOS, 143B, SJSA‐1, U2OS and U2OS/MTX300) showed much higher values than the hFOB1.19 cell line." (PMID 35060345, 2022). "In osteosarcoma, MIF activates the RAS/MAPK pathway to promote osteosarcoma cell proliferation and migration." (PMID 35060345, 2022). "Mechanistically, we demonstrated that the transcriptional regulation of c‐Myb was mediated by MIF through the NF‐κB/P‐TEFb complex in osteosarcoma." (PMID 35060345, 2022). "MIF inhibitor 4‐IPP interrupted the MIF/CD74‐induced NF‐κB/P‐TEFb complex‐mediated c‐Myb transcription in osteosarcoma." (PMID 35060345, 2022). "Our findings demonstrate that the small molecule 4‐IPP targeting the MIF protein exerts an anti‐osteosarcoma effect by simultaneously inactivating the biological functions of MIF and promoting its proteasomal degradation." (PMID 35060345, 2022). "The overexpression of MIF/CDK9/c‐Myb can significantly reverse the therapeutic effect of 4‐IPP on osteosarcoma." (PMID 35060345, 2022). "In this study, overexpression of MIF can reverse the inhibitory effect of 4‐IPP on osteosarcoma, and knockout of MIF can abolish this effect." (PMID 35060345, 2022). "We collected 40 samples of osteosarcoma at different stages and performed immunohistochemical detection of MIF." (PMID 35060345, 2022). "In line with the heterogeneity of osteosarcoma, we found subpopulations of osteosarcoma cells that highly expressed COL6A1, COL6A3 and MIF and were closely associated with lung metastasis." (PMID 35463309, 2022). "In this study, we identified the MIF inhibitor 4‐IPP as a specific double‐effector drug for osteosarcoma with both anti‐tumour and anti‐osteoclastogenic functions." (PMID 35060345, 2022). "Previous studies indicated that hypoxia promoted osteosarcoma development through increasing immunomodulatory proteins such as macrophage migration inhibitory factor (MIF), Galectin-1, and so on." (PMID 33816483, 2021). "Other example has been the antibody against MIF (macrophage migration inhibitory factor) which inhibited tumor angiogenesis and lymphangiogenesis in mice model of osteosarcoma." (PMID 29072623, 2017).
osteosarcoma (continued). "Collectively, these findings highlight a MIF-driven communication axis between malignant osteosarcoma cells and T cells that may underpin immune evasion and therapeutic resistance mechanisms." (PMID 41346635, 2025). "Finally, in osteosarcoma, MIF promotes the growth and lung metastasis of osteosarcoma by activating RAS/MAPK pathway." (PMID 37715019, 2023). "In addition, other MIF inhibitors including 4-IPP and Chicago sky blue 6B (CSB6B) have also been reported to suppress MIF-induced osteoclastogenesis and osteosarcoma tumorigenesis by targeting NF-κB signaling." (PMID 35563296, 2022). "Direct destabilization of the MIF protein with 4‐IPP may be a promising therapeutic strategy for treating osteosarcoma." (PMID 35060345, 2022). "However, 4‐IPP still interrupted MIF‐mediated communication between osteosarcoma cells and osteoclasts, thus promoting osteoclastogenesis." (PMID 35060345, 2022). "However, in the tumour microenvironment of osteosarcoma, how exactly MIF affects osteoclast production remains to be explored." (PMID 35060345, 2022). "The high-risk group was enriched with the MIF signaling pathway, the CLEC signaling pathway, which was previously reported to be associated with osteosarcoma growth and metastasis, and the vascular endothelial growth factor (VEGF) signaling pathway, which promotes blood vessel growth." (PMID 36275664, 2022). "Here, MIF expression in osteosarcoma samples at different stages was tested." (PMID 35060345, 2022). "We further explored whether MIF derived from osteosarcoma cells has an effect on osteoclast differentiation in vitro." (PMID 35060345, 2022). "Studies have also reported the potential role of these receptors in osteosarcoma, and whether these effects are related to MIF remains to be studied." (PMID 35060345, 2022). "We further tested the ubiquitination of MIF treated with 4‐IPP in osteosarcoma." (PMID 35060345, 2022). "Our research initially explores the role of MIF/CD74 in osteosarcoma." (PMID 35060345, 2022). "In osteosarcoma, MIF activates the MAPK pathway to promote lung metastasis as well as tumour growth, indicating that immunotherapy targeting MIF may represent a viable and promising treatment for osteosarcoma." (PMID 35060345, 2022). "We performed further experiments to explore whether 4‐IPP plays an anti‐tumour role in osteosarcoma by participating in MIF rescue." (PMID 35060345, 2022). "DARTS was used to clear the interaction between 4‐IPP and MIF protein in osteosarcoma cells." (PMID 35060345, 2022). "SPP1, VEGFA, EMMPRIN, MIF, uPAR, Angiogenin, and Cystatin C were among the most highly expressed analytes in both patient specimens and in cell line conditioned media, demonstrating that the osteosarcoma cells themselves are a cellular source of these molecules." (PMID 39896512, 2025). "Furthermore, we tested the expression of MIF in various osteosarcoma cell lines." (PMID 35060345, 2022). "M2 macrophages communicated with osteoblasts by the APP, MIF, and SPP1 signaling pathways, facilitating osteosarcoma development." (PMID 40092698, 2025). "Outgoing and incoming signalling pattern analyses indicated that signalings such as Collagen, MK, MIF, PTN and CD99 dominated the intercellular communication modes among cells within osteosarcomas." (PMID 39834330, 2025). "Importantly, tumor-derived MIF has been shown to drive NF-κB activation, proliferation, and metastasis, while pharmacologic destabilization or neutralization of MIF suppresses tumor progression and enhances responses to PD-1 blockade, supporting its translational relevance in osteosarcoma." (PMID 41346635, 2025). "M2 macrophages communicated with osteoblastic cells via the APP, MIF, and SPP1 signaling pathways, facilitating osteosarcoma development." (PMID 40092698, 2025). "The group with the worst EFS and OS for osteosarcoma and Ewing sarcoma, Group 1, was defined by an increase in CXCL5, CXCL12, and MIF." (PMID 41008853, 2025).
osteosarcoma (continued). "The one gene that was in the top ten most negatively correlated genes for both tags was macrophage migration inhibitory factor (MIF), a pleiotropic pro-inflammatory cytokine involved in osteosarcoma progression." (PMID 38799575, 2024). "MIF inhibitor 4‐IPP reduced the proliferation and metastasis of osteosarcoma cells by suppressing the NF‐κB pathway." (PMID 35060345, 2022). "Mechanistically, PLEK may exert its effects through macrophage-derived cytokine signaling pathways, such as the MIF and TNF pathways previously identified as active in macrophage-osteosarcoma cell communication." (PMID 40895569, 2025). "In this study, we provide evidence that the MIF inhibitor 4‐IPP has an anti‐tumour effect on osteosarcoma by promoting the degradation of the MIF protein and inhibiting the transcription of c‐Myb through hampering the formation of the downstream NF‐κB/CDK9 complex in osteosarcoma." (PMID 35060345, 2022). "The effect of MIF inhibitors on osteosarcoma has not been clarified, and an inhibitor that targets MIF to treat osteosarcoma remains to be identified." (PMID 35060345, 2022). "Although 4‐iodo‐6‐phenylpyrimidine (4‐IPP) can inactivate MIF biological functions, its anti‐osteosarcoma effect and molecular mechanisms have not been investigated." (PMID 35060345, 2022). "After the NF‐κB pathway was identified as a direct downstream target of MIF by 4‐IPP, we further investigated whether a certain exact proto‐oncogene is regulated by NF‐κB in osteosarcoma." (PMID 35060345, 2022). "Given that the downstream pathway of MIF/CD74 in osteosarcoma is unknown, we used rhMIF and CD74 neutralizing antibodies to verify the effect of MIF/CD74 on NF‐κB pathway." (PMID 35060345, 2022). "Although fibroblastic osteosarcoma specimen OS-7 did not exhibit the readily discernable spatial differences in CXCR4, CXCL12, and MIF expression observed in the other specimens, ligand-receptor analysis did indeed provide evidence of regional differences in the CXCR4 signaling axis." (PMID 39896512, 2025).
nasopharyngeal carcinoma (21 papers, 2013 to 2025). A carcinoma arising from the nasopharyngeal epithelium. "This shows that MIF is a high-risk factor that promotes the metastasis of nasopharyngeal carcinoma." (PMID 35036405, 2021). "It has also been shown that increased MIF expression in tumor-infiltrating lymphocytes (TILs) within tumor microenvironments was associated with better outcomes in nasopharyngeal carcinoma (NPC) patients." (PMID 32155795, 2020). "Exosomes derived from nasopharyngeal carcinoma (NPC) release macrophage migration inhibitory factor (MIF)." (PMID 40328736, 2025). "In nasopharyngeal carcinoma, MIF promotes the formation and migration of Th17 cells mediated by the MIF-CXCR4 axis and dependent on the mTOR pathway." (PMID 35842634, 2022). "Similarly, exosome-derived MIF from nasopharyngeal carcinoma promotes metastasis by enhancing macrophage survival." (PMID 39495793, 2024). "It has been discovered that MIF is highly expressed in nasopharyngeal carcinoma cells, and exosomes secreted by nasopharyngeal carcinoma cells can be ingested by macrophages, thus inhibiting ferroptosis in macrophages and eventually promoting nasopharyngeal carcinoma metastasis." (PMID 36845720, 2023). "MIF secreted by nasopharyngeal carcinoma could suppress ferroptosis of macrophages and then increase the rate of metastasis." (PMID 35603151, 2022). "Relationship between MIF expression and clinical pathological factors of nasopharyngeal carcinoma." (PMID 35036405, 2021). "To assess the effects of Epstein–Barr virus (EBV) and human papillomavirus (HPV) infection on the tumor microenvironment, we examined the relationship between viral infection status, macrophage migration inhibitory factor (MIF), and tumor-associated macrophages in nasopharyngeal carcinoma (NPC)." (PMID 34407796, 2021). "Macrophage migration inhibitory factor (MIF), overexpressed in nasopharyngeal carcinoma (NPC) cells, significantly inhibits ferroptosis in macrophages, which is conducive to NPC metastasis." (PMID 35327582, 2022). "Recent studies have demonstrated that MIF and CXCR4 were overexpressed in a number of cancers, including gastric cancer, breast cancer, prostate cancer, colon cancer and nasopharyngeal carcinoma." (PMID 23497377, 2013). "In nasopharyngeal carcinoma (NPC) cell lines, C666-1, MIF/IL-8/ CXCR2 signaling could enhance the growth of the tumor spheres." (PMID 27788497, 2017). "The results showed higher expression of MIF in NPC patients vs. normal controls and higher expression in clinical stage III-IV NPC patients than in clinical stage I-II patients, which suggested that the upregulation of MIF level may be closely related to end-stage nasopharyngeal carcinoma." (PMID 35036405, 2021).
ischemic stroke (20 papers, 2012 to 2025). A stroke disorder caused by obstruction of blood flow to the brain, due to thrombotic (local blood clot formation) or embolic (due to a blood clot or other material traveling from another site) event. "The study demonstrated that polymorphisms in the MIF gene promoter were associated with CAA severity in ischemic stroke patients and these genetic variants may serve, in the next future, as markers for an individual's susceptibility to CAA." (PMID 27298828, 2016). "In order to identify detection and treatment targets, studies have detected the lineage changes of various cytokines/chemokines in the plasma of ischemic stroke patients, and confirmed that MIF is significantly elevated." (PMID 36824264, 2023). "For example, MIF knockout mice reduced neuronal death after ischemic stroke and promoted recovery of neurological function in mice." (PMID 36797398, 2023). "The purpose of this study was to explore the neuroprotective effect of the MIF in the in vivo middle cerebral artery occlusion (MCAO) mouse model of ischemic stroke." (PMID 35805977, 2022). "During ischemic stroke, MIF interacts with apoptosis-inducing factor (AIF) to translocate from the cytosol to the nucleus to cause DNA fragmentation and neuronal death." (PMID 35585040, 2022). "Here, we discovered that genetic ablation or pharmacological inhibition of HDAC6 reduced brain injury after ischemic stroke by increasing macrophage migration inhibitory factor (MIF) acetylation." (PMID 35585040, 2022). "Previous studies have reported that MIF plays a protective role in ischemic stroke by suppressing apoptosis, whereas others have described MIF as having a detrimental effect by promoting inflammation or disrupting the tight junction in brain endothelial cells." (PMID 33672416, 2021). "A previous study has reported that the median serum MIF concentration in 292 patients with ischemic stroke was 20.6 ng/mL." (PMID 33672416, 2021). "In these studies, we found that MIF was neuroprotective in ischemic stroke models via the inhibition of neuronal cell apoptosis and induction of brain-derived neurotrophic factor (BDNF) expression." (PMID 33672416, 2021). "This study provides detailed information on MIF administration, which offers a foundation for future in vivo studies and translation into novel therapeutic strategies for ischemic stroke." (PMID 33672416, 2021). "The results revealed that MIF expression was downregulated in ischemic stroke patients vs. normal control in the GSE16561 dataset (p = 0.022), while it was upregulated in the GSE140275 dataset (p = 0.0018)." (PMID 34707562, 2021). "Macrophage migration inhibitory factor (MIF), is one such cytokine that is elevated following CNS injury, and is associated with the prognosis of TBI, and ischemic stroke." (PMID 31906137, 2019). "The higher expression of activated astrocyte infers the severity of ischemic stroke in MIF-treated rats." (PMID 29335619, 2018). "Given that CSVD and ischemic stroke, and VCI and AD have similar pathogenesis, MIF may be involved in multiple pathogenesis of CSVD leading to VCI, and MIF can cause CI through AD-related pathological processes." (PMID 36824264, 2023). "Many studies have shown that MIF plays a crucial role in ischemic stroke, AD, and other diseases." (PMID 36824264, 2023). "Importantly, MIF K78Q mice, which mimic the biochemical effects of K78-acetylated MIF, displayed reduced infarct brain injury and improved behavioral deficits after ischemic stroke, indicating that MIF K78 acetylation has neuroprotective effects." (PMID 35585040, 2022). "On the other hand, hypoxia may be involved in neurological diseases such as ischemic stroke, and a few studies reported that MIF plays a beneficial role in neurological recovery after ischemic stroke." (PMID 35324982, 2022). "We investigated whether the MIF promotes neurological recovery in an in vivo mouse model of ischemic stroke." (PMID 35805977, 2022).